EI24 (EI24 autophagy associated transmembrane protein)
Diseases named in the same sentence as EI24 in open-access papers (continued):
Sharing a sentence is not in itself a finding about the gene and the disease.
tumor (continued). "Collectively, data from clinical tumor samples reinforce the important role of EI24 in suppressing tumor malignancy." (PMID 24280371, 2013). "The pro-apoptotic gene EI24 plays an important role in the negative regulation of cell growth through its tumor suppressor activities." (PMID 24280371, 2013). "Collectively, these findings establish EI24 as a critical suppressor of tumor progression and implicate EI24 expression level in malignant tumors as a useful therapeutic and diagnostic marker." (PMID 24280371, 2013). "It has been suggested that EI24 acts as a pro-apoptotic factor and prevents tumor spreading in mammals." (PMID 18070355, 2007). "Further studies should be conducted to see whether EI24 exerts this tumor-promoting role in other stress circumstances, such as hypoxia, genome instability, etc., which are well established as hallmarks of cancer." (PMID 40253325, 2025). "Hsa_circ_0043278 acts as a tumour suppressor gene in BC through the hsa_circ_0043278/miR-455-3p/EI24 axis and may be regarded as a new prognostic predictor or potential therapeutic target in BC." (PMID 34800978, 2021). "In addition, EI24 was reported to be a direct target of miR-455-3p and to act as a tumour suppressor gene in triple-negative BC (TNBC)." (PMID 34800978, 2021). "Therefore, the function of EI24 as an essential component of autophagy conflicts with its known tumor suppressor role, because autophagy promotes tumor cell survival." (PMID 31396480, 2019). "Additionally, it has been reported that EI24 is involved in the survival and growth of non-tumor cells such as pancreatic β-cells and Dictyostelium discoideum." (PMID 31396480, 2019). "This newly discovered role of EI24 as a component of autophagy may act as a tumor promoter, which is contradictory to its known role as a tumor suppressor." (PMID 31396480, 2019). "Downregulation of EI24 may result in a deregulated tumor suppression system and promoted tumorigenesis." (PMID 30369947, 2018). "Thus, attenuation of NF-κB signaling by endogenous EI24 is crucial for the suppression of inflammation-induced tumor progression." (PMID 24280371, 2013). "In contrast, ectopic expression of EI24 in tumor cells suppressed malignant progression." (PMID 24280371, 2013). "Beyond regulating development, the miRNAs described here may also have important consequences for cancer, as both Casp2 and Ei24 are considered tumor suppressors." (PMID 21573140, 2011). "Notably, these findings could link the EI24 low expression level in PDAC with its tumor suppressor role." (PMID 30369947, 2018). "However, the involvement of EI24 in tumor malignancy and the underlying molecular mechanisms are not well characterized." (PMID 24280371, 2013). "We used clinical samples from cancer patient-based datasets to investigate the role of EI24 in EMT and tumor progression." (PMID 24280371, 2013). "Taken together, these results support a model in which EI24 coordinates EMT and tumor progression through the regulation of TRAF2-mediated NF-κB activity." (PMID 24280371, 2013).
tumor (continued). "Furthermore, diminished expression of EI24 contributes to the induction of epithelial-to-mesenchymal transition (EMT), as well as tumor growth." (PMID 32974192, 2020). "Additional genes that had similar DNA and RNA frequency as DUSP5 and EI24 but no previous research on their potential role as a tumor suppressor were UBXN11, CAPN15, C6orf62, GPRIN1, KIAA2018, PCDHGA10, and PCGF1." (PMID 31484939, 2019). "EI24 functions as a tumor suppressor and plays an important role in the negative regulation of cell growth and induction of apoptosis." (PMID 30369947, 2018). "In this study, we examined the functional significance of EI24 in the regulation of EMT and tumor progression by investigating the properties of cancer cells in which EI24 was either overexpressed or downregulated and the physiological activity of these cells in a mouse model of cancer." (PMID 24280371, 2013). "This is not the first report that EI24 acts as a tumor promoter." (PMID 31396480, 2019). "Whether the functions of EI24 in autophagy are related with its activities in tumor cells is not yet clear." (PMID 30369947, 2018).
cancer (13 papers, 2011 to 2025). A tumor composed of atypical neoplastic, often pleomorphic cells that invade other tissues. "The limited data indicate that EI24 has been implicated in cell growth, apoptosis, migration, and infiltration of cancer cells." (PMID 32974192, 2020). "EI24 has been previously linked with inhibiting cancer cell growth and proapoptotic functions." (PMID 30369947, 2018). "Collectively, these studies indicate that the expression level of EI24 in malignant tumors could be a useful diagnostic marker." (PMID 24280371, 2013). "Furthermore, expression of EI24 was linked to enrichment of arginine metabolism pathway as well as poor survival of patients with cancer across various cancer types, suggesting its role in cancer resistance to arginine deprivation." (PMID 40253325, 2025). "This study is the first to report the role of EI24 in promoting cancer survival via translational regulation of the metabolic enzyme ASS1, thus paving a route for further investigation into the link between EI24 and cancer metabolism." (PMID 40253325, 2025). "The results showed that overexpression (OE) of EI24 increased cancer cell viability in such conditions." (PMID 40253325, 2025). "The results of this study elucidate the multifaceted roles of EI24 in regulating various cellular processes, including cancer proliferation, autophagy, and homeostasis." (PMID 40556865, 2025). "EI24 was overexpressed in cancer cells using a doxycycline-inducible system or adenovirus transduction, while siRNA was used to knockdown EI24." (PMID 40253325, 2025). "Herein, we report the enhanced regulation of ASS1 protein translation in cancer cells upon arginine starvation, interestingly via a novel function of etoposide-induced protein 2.4 homolog (EI24)." (PMID 40253325, 2025). "Aberrant expression of EI24 has been reported in various cancer types and is closely related to poor prognosis." (PMID 32974192, 2020). "IPA system for analysis of the microarray data also revealed that EI24 silencing gave rise to dysregulation of several diseases and biofunctions, including cancer, organismal injury and abnormality, cell death, and survival." (PMID 32974192, 2020). "Although the biological relevance of EI24 has been evidenced only in cancer, it seems reasonable to consider its action as a mechanism of pathogenesis of any disorder associated with impaired clearing of cellular debris." (PMID 30626110, 2019). "Overexpression of EI24 suppressed cancer cell growth in vitro and in vivo and induced cell cycle S phase arrest, with no impact on caspase-dependent apoptosis." (PMID 30369947, 2018). "EI24’s functions in cancer biology are highly context-dependent." (PMID 40556865, 2025). "Next, to investigate whether EI24 is important for cancer cells during arginine deprivation, we overexpressed EI24 using doxycycline in MDA-MB-231 and adenovirus in Hs 578T." (PMID 40253325, 2025). "Similarly, while the functions of EI24 in cancer are still under debate, we suggest that EI24 helps cancer cells overcome exhausting conditions such as metabolic limitation, as in this study." (PMID 40253325, 2025). "Meanwhile, the function of etoposide-induced 2.4 homolog (EI24) in cancer metabolism, and specifically in arginine metabolism, remains unknown." (PMID 40253325, 2025). "It is known that to counteract pro-apoptotic stimuli, cancer cells might activate pro-survival mechanisms, an event that could explain the decreased expression levels of EI24 and RERE proteins in response to CK2 inhibition with CIGB-300." (PMID 35359604, 2022). "Besides Beclin1 and EI24, the altered expression of several autophagy proteins such as Atg5 and UVRAG are also reported to be associated with various human cancers." (PMID 30717078, 2019).
cancer (continued). "Because the increased cell motility, cytoskeleton rearrangements, and decreased cell-cell adhesion induced by reduced levels of EI24 are reminiscent of EMT, we examined whether EI24 ablation affected the epithelial characteristics of cancer cells." (PMID 24280371, 2013). "Furthermore, our data showed that decreased EI24 expression correlated with high tumorigenic potential of various cancer cells and with poor prognosis in human cancer patients." (PMID 24280371, 2013). "Further extensive investigations are needed to elucidate the precise role of EI24 in these cancers." (PMID 24280371, 2013). "Hence, by showing that EI24 may significantly benefit cancer cell adaptation to restricted arginine levels, this study hopes to shed the first light on the role of EI24 in the context of cancer metabolism." (PMID 40253325, 2025). "The potential regulation of EI24 by Akt is of considerable interest, as it may represent a mechanism by which Akt mediates cell survival and apoptosis, an important finding in light of the clear role of Akt in the context of cellular proliferation and cancer." (PMID 23684622, 2013). "According to these well-established functions of EI24, GNGT2 and MIR21, PanDM’s identification of their DM status in cancers is highly likely to reflect a biological reality." (PMID 33087120, 2020). "It was reported that the protein EI24 (etoposide-induced protein 2.4 homolog) promoted degradation of RING E3 ligases in autophagy, which can be important in cancer transformation." (PMID 30626110, 2019). "In the current study, to clarify the role of EI24 in PDAC, we examined the expression and functions of EI24 in PDAC tissues and cancer cell lines compared with controls and its effects on tumorigenesis in vivo." (PMID 30369947, 2018). "Since EMT is a characteristic feature of malignant tumors, we investigated cellular properties that are accompanied by EMT in the context of EI24 dysregulation." (PMID 24280371, 2013).
infection (1 paper, 2020). The state of being infected such as from the introduction of a foreign agent such as serum, vaccine, antigenic substance or organism. "The canonical pathway enrichment analysis of IPA indicated that the acute phase response signaling pathway was remarkably inhibited upon EI24 overexpressing, which was associated with inflammatory reactions induced in response to tissue injury or infection." (PMID 32974192, 2020).
metabolic disorders (1 paper, 2025). "Future studies should aim to elucidate the molecular pathways through which Ei24 exerts its effects and explore its potential in clinical settings for managing metabolic disorders and promoting healthy aging." (PMID 40556865, 2025).
EI24 also shares sentences with these, for which no sentence is quoted: chronic heart failure (1 paper); colorectal cancer (1); glioblastoma (1); hypertrophic cardiomyopathy (1); hypopharyngeal carcinoma (1); invasive lobular breast carcinoma (1); lung carcinoma (1); mixed ductal/lobular carcinoma (1); osteosarcoma (1).